MIR8063 (microRNA 8063)
Synonyms: hsa-mir-8063
Gene: MicroRNA gene on chromosome 15 (36,972,821 to 36,972,901, reverse strand). Ensembl gene ENSG00000277202.
Homologues: Orthologues: chimpanzee MIR8063 (100% identical).